Y_RNA (Y RNA )
Gene: Miscellaneous RNA gene on chromosome 12 (7,850,717 to 7,850,818, reverse strand). Ensembl gene ENSG00000201663.
Homologues: Orthologues: chimpanzee Y_RNA (99% identical), macaque Y_RNA (93% identical). Paralogues in human: Y_RNA (87% identical), Y_RNA (84% identical), Y_RNA (83% identical), RNY3P1 (82% identical), Y_RNA (82% identical), RNY3 (81% identical), Y_RNA (81% identical), RNY3P14 (80% identical), RNY3P4 (80% identical), Y_RNA (80% identical), RNY3P11 (79% identical), RNY3P12 (79% identical), and 91 more.